TNFAIP3 (TNF alpha induced protein 3)
Diseases named in the same sentence as TNFAIP3 in open-access papers (continued):
Sharing a sentence is not in itself a finding about the gene and the disease.
breast carcinoma (continued). "In breast cancer (BC), OTUD5, YOD1, OTUD6A, OTUD7B, ZRANB1, and TNFAIP3 were characterized as carcinogenic drivers." (PMID 40469292, 2025). "A higher expression of TNFAIP3 was found in the TNBC subgroup of the METABRIC cohort, as compared to other breast cancer samples (p-value < 2.2 × 10−16)." (PMID 38201582, 2023). "It has been reported that hormone-induced expression of Birc3 and Tnfaip3, target genes of the RANK-TRAF6-mediated canonical NF-κB pathway in normal epithelial cells, in luminal-like breast cancers are involved in cancer cell survival and chemoresistance." (PMID 31396572, 2019). "In addition, several regulatory genes in the IL-17 signaling pathway, such as TNFAIP3, TRADD, and IKBKE, were also observed to be correlated with PD-1 and/or PD-L1 in one or more cohorts of breast cancer samples." (PMID 33102239, 2020). "For instance, it was reported that TNFα induces a cytotoxic effect in luminal breast cancer cell lines in absence of ubiquitin editing enzyme TNFα-induced protein 3 (TNFAIP3 also called A20), but this protein has a wide range of effects in different tissues." (PMID 32391269, 2020). "It remains therefore unclear whether upregulation of NF-κB signaling aids to sensitize cells to Bortezomib or increases drug resistance in breast cancer and whether hsa-let-7a-5p increases Bortezomib sensitivity via downregulation of NKIRAS2 and TNFAIP3." (PMID 31063487, 2019). "Simultaneous treatment of MCF7 and SUM52PE breast cancer cells with acidosis and hypoxia may induce the expression of inflammatory response genes such as tumor necrosis factor alpha (TNF-α) and tumor necrosis factor alpha-induced protein 3 (TNFAIP3)." (PMID 25988385, 2015). "Importantly, KO of TNFAIP3 inhibited tumor growth promoted by both mutant H-Ras and FGFR1 activation, suggesting that TNFAIP3 may serve as a potential target for inhibiting ER- breast cancer with active mutant Ras and/or active FGFR1 signaling." (PMID 30111373, 2018). "By mass spectrometry analysis performed in a breast cancer stem cell model (human mammary epithelial HMLER CD24low/CD44high), salinomycin, a ferroptosis inducer, was capable of inducing protein upregulation of CD274 and TNFAIP3 without any modulation of PDCD1." (PMID 38201582, 2023).
inflammatory bowel disease (21 papers, 2011 to 2024). A spectrum of small and large bowel inflammatory diseases of unknown etiology. "Several of these TNFAIP3-associated diseases including type 1 diabetes, celiac disease and inflammatory bowel disease, are known to involve loss of intestinal barrier function." (PMID 22031828, 2011). "TNFAIP3, which encodes the A20 protein, is linked genetically and epigenetically to inflammatory bowel disease (IBD)." (PMID 31295268, 2019). "Some diseases related to TNFAIP3, such as inflammatory bowel diseases, involve the function of intestinal barrier." (PMID 35565618, 2022). "The increasing diffusion of genome-wide analysis techniques has shown that common low-penetrance non-coding variants in TNFAIP3 can be found in many autoimmune diseases including SLE, psoriasis, inflammatory bowel disease (IBD), type 1 diabetes, and others." (PMID 34198614, 2021). "TNFAIP3 may also impact inflammatory bowel diseases by interacting with autophagy-related 16-like 1 (ATG16L1) protein." (PMID 39125844, 2024). "The inflammation and inflammatory bowel disease (IBD) disorders had many commonly modulated genes that were also found in the String analysis that were common with the disorders which included IL-8, ICAM1, RELB, NFκBIA, TNFAIP3, LIF, CXCL1, CXCL2, CXCL3, CXCL10, and TNF-α." (PMID 28099447, 2017).
type 1 diabetes (21 papers, 2010 to 2024). "For the MIR3681HG (rs1534422) and TNFAIP3 (rs2327832) genotypes, an increased risk for progression was observed only in children born by Caesarean section and with the type 1 diabetes-susceptible MIR3681HG GG genotype or TNFAIP3 GG genotype." (PMID 38819466, 2024). "Germline SNPs in TNFAIP3 (encoding A20) are associated with Crohn's disease, coeliac disease, type 1 diabetes, RA, coronary artery disease in type 2 diabetes, systemic sclerosis, psoriasis and systemic lupus erythematosus (SLE)." (PMID 34269817, 2021). "Type 1 diabetes susceptibility genes have previously been found to interact with Caesarean section (IFIH1) or to be associated with increased progression to stage 3 type 1 diabetes (TNFAIP3, CTSH, MIR2681HG)." (PMID 38819466, 2024). "TNFAIP3 was suggested to be associated with type 1 diabetes." (PMID 28744461, 2017). "SNPs ~ 185 kb upstream from the TNFAIP3 gene have a strong association with risk of RA, type 1 diabetes (T1D), celiac disease (CeD), and Crohn's disease." (PMID 26339139, 2015). "Furthermore the TNFAIP3 gene (located on chromosome 6q23) has been identified as a susceptibility locus in genome-wide association studies for several human autoimmune inflammatory disorders including IBD, celiac disease, psoriasis, lupus, rheumatoid arthritis and type I diabetes." (PMID 22031828, 2011).
Behcet disease (18 papers, 2014 to 2026). A chronic, relapsing, multisystemic vasculitis characterized by mucocutaneous lesions, as well as articular, vascular, ocular and central nervous system manifestations. "Beyond Behçet syndrome, TNFAIP3 variants have also been implicated in SLE, rheumatoid arthritis, Crohn disease, and other autoimmune conditions." (PMID 39964335, 2025). "In Behçet syndrome, rare variants in TNFAIP3, RELA, and NFKB1 genes have been identified, underscoring the importance of NF‐κB overactivation." (PMID 39964335, 2025). "Deleterious TNFAIP3 variants cause a Behçet’s disease–like autoinflammatory phenotype including retinal vasculitis." (PMID 39403923, 2024). "In 2016, heterozygous loss-of-function mutations in TNFAIP3 leading to haploinsufficiency of its encoded protein, A20, were identified as a monogenic cause of Behçet disease." (PMID 38022498, 2023). "For instance, a mutation in TNFAIP3 (A20) that deubiquitinate IκB kinase beta leads to hyperactivation of the NFκB pathway, and the patients with TNFAIP3 mutation exhibit various symptoms resembling Behcet diseases, SLE, or others." (PMID 33766139, 2021). "More recently, in cases with familial Behcet's disease, heterozygous TNFAIP3 mutations have been identified and the designation haploinsufficiency of A20 (HA20) has been given." (PMID 32256502, 2020). "Recently, heterozygous germline mutations in the TNFAIP3 gene have been found to cause the haploinsufficiency of A20 (HA20), which displays an early-onset autoinflammatory disease resembling Behçet’s disease." (PMID 31299923, 2019). "Additionally, dysfunctions in the binding of TNFα-induced protein 3 (TNFAIP3), also known as A20, a regulator of NEMO, can lead to bowel inflammation, arthritis, and oral and genital ulceration similar to Behçet disease, associated with immunodeficiency." (PMID 40649913, 2025). "Chronic nonbacterial osteomyelitis (CNO), DADA2, PFAPA, Behcet disease, PAPA syndrome, Blau syndrome, CANDLE and TNFAIP3-associated autoinflammatory syndrome were less common (2.6%, 2.2%, 2.2%, 1.8%, 0.9%, 0.9%, 0.4% and 0.4%) respectively." (PMID 36096831, 2022). "Furthermore, the silencing of TNFAIP3 increased JNK and p38 activation but did not affect ERK1/2 in Behcet's disease." (PMID 32280718, 2020).
celiac disease (18 papers, 2011 to 2025). An autoimmune genetic disorder with an unknown pattern of inheritance that primarily affects the digestive tract. "A20, encoded by the TNFAIP3 gene, is a protein linked to Crohn’s disease and celiac disease in humans." (PMID 40892518, 2025). "Moreover, variants of TNFAIP3 are also known risk factors for celiac disease and are implicated in altered NF-κB signaling." (PMID 27767057, 2016). "The TNFAIP3 gene is well conserved between murine and human genomes, and A20 polymorphisms and mutations are associated with human IBD and celiac disease." (PMID 40892518, 2025). "a common inflammatory response pathway is highlighted by the correlation between the function of HLA-DQB1 in antigen presentation in celiac disease and TNFAIP3 in the NF-KB pathway in NHL." (PMID 40321894, 2025). "TNFAIP3 is involved in regulation of the nuclear factor kappa B (NF-kB) inflammatory signaling pathway in pathology of coeliac disease and is one of the key mediators in this nuclear activating complex." (PMID 33585005, 2020). "In our analysis we focused on NFKBIA gene, as well as on RELA and TNFAIP3 genes that, similarly to NFKBIA, have been associated with susceptibility to celiac disease." (PMID 31049595, 2019). "A20/TNFAIP3 is genetically linked to IBD and celiac disease via GWAS." (PMID 40892518, 2025).
Crohn disease (18 papers, 2010 to 2025). A gastrointestinal disorder characterized by chronic inflammation involving all layers of the intestinal wall, noncaseating granulomas affecting the intestinal wall and regional lymph nodes, and transmural fibrosis. "The physiological importance of A20 in intestinal pathology is further strengthened by the identification of A20/TNFAIP3 polymorphisms associated with Crohn’s disease, ulcerative colitis, and celiac disease." (PMID 31015422, 2019). "Reduced expression of TNFAIP3 in the intestinal mucosa has been observed in patients with Crohn’s disease." (PMID 36498846, 2022). "Mucosal biopsies from Crohn's disease patients with moderate to severe disease are characterized by low TNFAIP3 expression." (PMID 22031828, 2011). "Some patients with Crohn’s disease have reduced expression of TNFAIP3." (PMID 39125844, 2024). "Indeed, mucosa taken from Crohn's disease patients with moderate to severe disease is characterized by low expression of TNFAIP3." (PMID 22031828, 2011).
viral infections (18 papers, 2017 to 2026). "To further explore how deltacoronavirus infection affects the expression of the TNFAIP3 gene, we investigated the pre-mRNA, circRNA, mRNA, and encoded protein of the TNFAIP3 gene during virus infection." (PMID 34781747, 2021). "Previous studies measuring TNFAIP3 in the serum using ELISA assays have been performed in the context of viral infections such as chronic Hepatitis B infections." (PMID 32709905, 2020). "Several reports have suggested that TNFAIP3 also restricts innate immune signaling in response to certain viral infections." (PMID 31703342, 2019). "Post PCV2 infection, we identified 199 differentially expressed lncRNAs, which appear to modify genes associated with viral infection, such as SOD2, TNFAIP3, ARG1, SERPINB2, VLDLR, HSPA5, and LCN2." (PMID 30863688, 2019). "Furthermore, 14 proteins that were upregulated after virus infection—including TNFaIP3, HNRNPH2, RSAD2, ISG20, IDO1, and KCNN4—also exhibited significantly increased mRNA levels relative to uninfected cells (p < 0.05)." (PMID 36423196, 2022). "Susceptibility to predominantly viral infections was observed in TET2, TPP2 and TNFAIP3 patients while chronic mucocutaneous candidiasis (CMC) and mendelian susceptibility to mycobacterial disease (MSMD) were characteristic of STAT1 GOF and IL12RB1 patients, respectively." (PMID 34447369, 2021). "Moreover, virus infection-induced TNFAIP3 can block the phosphorylation and dimerization of IRF3 and inhibit the TLR3-induced activation of NF-κB and IFN-β." (PMID 34781747, 2021). "The MERS-CoV-shared genes KRT6B and TNFAIP3 had a high p-value associated with SARS-CoV-2, whereas genes such as OAS1-3, IRF9, IRF7, STAT1, PML and IFIH1 were highly associated with host responses to viral infections and type I interferon." (PMID 33301474, 2020). "In addition, the tumor necrosis factor, alpha-induced protein 3 (TNFAIP3), is a central regulator of immunopathology and is associated with the maintenance of immune homeostasis and severe viral infections." (PMID 33301474, 2020). "For example, TNFAIP3 is involved in influenza A virus infection, whereas ARG1 suppresses arthritogenic alphavirus infection Therefore, PCV2 infection-associated lncRNAs may modulate viral infection through regulating these targeted genes." (PMID 30863688, 2019). "TNFAIP3, ULBP1 and TIAM1 were consistently down-regulated by viral infection, while CCL8, CCL11, CXCL11, NCF2, CSF3 and PRKCB were significantly up-regulated after infection." (PMID 28938587, 2017). "Previously, it has been reported that in viral infections, m6A often positively correlates with gene expression in immune response pathways, as immune response genes are more active with higher m6A levels, like IFIH1, TNFAIP3, IFIT1 and IFIT2." (PMID 40989927, 2025). "TNFAIP3 and TNFAIP6 have been reported to regulate innate immune response to viral infection." (PMID 39285245, 2024). "Additionally, DEGs related to the response to viral infections, such as DDIT4, CXCR4, EIF5A, TNFAIP3, BCL2, and IRF1, were also upregulated in NBs." (PMID 38440735, 2024). "Hence, IFIH1, TNFAIP3, IFIT1 and IFIT2 were the common immune response genes regulated by m6A during bacterial or viral infection, or LPS treatment." (PMID 35288544, 2022).
B-cell lymphomas (17 papers, 2012 to 2024). "In two cases, TNFAIP3 missense mutations were found, which are associated with a diagnosis of B-cell lymphoma including DLBCL." (PMID 37951851, 2024). "TNFAIP3 is a negative regulator of NF-κB that has been implicated as a tumor suppressor in multiple types of B-cell lymphoma including DLBCL." (PMID 37047075, 2023). "A coding TNFAIP3 variant, namely rs2230926, has been previously linked to B cell non-Hodgkin's lymphoma (NHL) development in patients with Sjogren's syndrome (SS) of French and UK origin." (PMID 30662920, 2018). "TNFAIP3 gene variants have been linked to the pathogenesis of both chronic inflammatory and autoimmune disorders and B cell lymphomas." (PMID 30662920, 2018). "Additionally, the mutation of TNFAIP3 has been widely studied in B-cell lymphoma, but its mutation pattern and impact on the prognosis of TCL patients are little known." (PMID 34526012, 2021). "However, we are still lacking information about the consequence of MYD88L265P in combination with TNFAIP3 loss in human B cell lymphoma." (PMID 30301877, 2018). "Loss of the tumor suppressor gene TNFAIP3 may lead to B-cell lymphomas." (PMID 35897075, 2022). "Examination of alterations in key pathways implicated in B-cell lymphomas suggests involvement in chromatin remodelling (CREBBP and EP300) and regulators of NF-κB signalling (TNFAIP3, BCL10, MYD88, CD79B and CARD11) were affected." (PMID 39460552, 2024). "Remarkably, some of these genes (KLF2, TNFAIP3, NOTCH1, HIST1H2BE) are recurrently mutated in HBsAgpos DLBCL and in HCV-associated B-cell NHL." (PMID 39055707, 2024). "Tumor necrosis factor alpha-induced protein 3 (TNFAIP3), a negative regulator of the NF-κB pathway, is a tumor suppressor gene in a variety of B cell lymphomas." (PMID 37884941, 2023). "Considering that the axis of this protein with its gene (TNFAIP3) represents a potent tumor suppressor gene in B-cell lymphoma, we investigated the measurement of TNFAIP3 mRNA levels across different B-cell subsets." (PMID 37176092, 2023). "The TNFAIP3 gene locus is located in chromosome band 6q23, and its deletion frequently occurs in B-cell lymphomas, particularly extranodal marginal zone B cell lymphoma and diffuse large B-cell lymphoma." (PMID 34526012, 2021). "Little is known about the expression correlation between BMPR2 and TNFAIP3 genes in B-cell lymphoma." (PMID 25364581, 2014). "We previously showed that TNFAIP3 is a common genetic target in B-cell lymphomas, following an analysis of 265 samples obtained from various B-cell lymphomas using either comparative genomic hybridization (CGH) or TNFAIP3 mutation analysis." (PMID 23039325, 2012). "Several protein coding transcript variants of the TNFAIP3 gene reported in B-cell lymphomas are predominantly nonsense or frameshift mutations." (PMID 29854308, 2018). "In addition, further biological studies are needed to determine if TGFβ2 and TNFAIP3 are therapeutic targets for B-cell lymphoma." (PMID 25364581, 2014). "TNFAIP3 inactivation has been reported in various B-cell lymphomas." (PMID 25364581, 2014). "However, it is conceivable that we did not detect homozygous deletions, which have been shown in other B-cell lymphoma subtypes and HL cell lines, and that we underestimated the frequency of involvement of TNFAIP3 in primary cHL cases." (PMID 23039325, 2012). "Additionally, in the different B-lymphocyte malignant cell lines, the expression levels of BMPR2, EP300, TGFβ2, and TNFAIP3 mRNA were quite different, which may be related to the heterogeneity of B-cell lymphoma." (PMID 25364581, 2014).